DNMT1 (DNA methyltransferase 1)
Diseases named in the same sentence as DNMT1 in open-access papers (continued):
Sharing a sentence is not in itself a finding about the gene and the disease.
breast cancer (continued). "In addition, a more recent study demonstrated that natural compounds such as EGCG, genistein, withaferin A, curcumin, resveratrol, and guggulsterone inhibit DNMT1, DNMT3a, and DNMT3b expression in breast cancer cell lines." (PMID 24822169, 2014). "However, expression levels of DNMT1 in breast cancer tissues have been a matter of debate, and the underlying mechanism is still not entirely clear." (PMID 24502362, 2014). "DNA methyltransferase 1 (DNMT1) plays a critical role in breast cancer progression." (PMID 24502362, 2014). "Five genomic loci corresponded to the criteria mentioned, and were further analyzed in the group of female Caucasian breast cancer patients and controls: DNMT1 SNP (A201G, rs2228612), DNMT3A SNPs (G301C, rs34843713 and G301A, rs34191084) and DNMT3B SNPs (C501T, rs406193 and G301A, rs35846833)." (PMID 23638630, 2013). "To date, no genetic polymorphisms have been reported for DNMT1 in association with breast cancer in the female Caucasian population." (PMID 23638630, 2013). "Statistical significance (P = 0.030) was identified for DNMT1 SNP (A201G, rs2228612): six women within the control group were GG homozygous (variant), while this mutation was absent in the breast cancer group." (PMID 23638630, 2013). "In particular, DNMT1-deficient breast cancer cells were not able to maintain promoter hypermethylation and exhibited decreased cell viability, whereas colorectal and bladder cancer cells were not affected." (PMID 21629434, 2010). "Moreover, elevated DNMT1 protein levels were observed in MCF-7 human breast cancer cells compared to normal human mammary epithelial cells." (PMID 21629434, 2010). "First, we observed DNMT1 staining in the cytoplasm, suggesting possible transportation of DNMT1 from the nucleus; Second, we detected active DNMT1 in extracellular vehicles (EVs) isolated from four different breast cancer cells, indicating that circulating DNMT1 can be excreted via EVs." (PMID 40317882, 2025). "Moreover, plasma DNMT1 levels increased progressively with advancing breast cancer stage." (PMID 40317882, 2025). "Therefore, we hypothesize that detecting DNMT1 could enable early warning and prognosis prediction for breast cancer." (PMID 40317882, 2025). "Therefore, we explored here the role of the DNA methyltransferase 1 (DNMT1) protein in CAF-dependent promotion of angiogenesis as well as the prognostic power of DNMT1 level in both cancer cells and their adjacent CAFs in locally advanced breast cancer patients." (PMID 35719957, 2022). "Whether DNMT1 plays a role in TAM-stimulated breast cancer metastasis remains unclear." (PMID 36273188, 2022). "Highly-expressed DNMT1 could promote chemotherapy resistance and metastasis of breast cancer." (PMID 35255904, 2022). "Therefore, we aim to reveal the mechanism of DNMT1 highly express in breast cancer." (PMID 36273188, 2022). "Consequently, designing specific small modulators that inhibit DNMT1 activity in order to restore the TSG RUNX3 could represent new clinical avenues for breast cancer therapeutics." (PMID 35898303, 2022). "Additionally, DNMT3B is co-expressed with DNMT1/3A in 3–5% of breast cancer samples." (PMID 35453496, 2022). "Collectively, our findings indicated that DNMT1 may inhibit miR-497 and boost the expression of GPRC5A through methylation, thus augmenting breast cancer chemotherapy resistance and metastasis, which provides novel mechanistic insight into the unrecognized roles of DNMT1 in breast cancer." (PMID 35255904, 2022). "However, molecular mechanism of DNMT1 regulating breast cancer still requires further study." (PMID 35109842, 2022). "Moreover, to evaluate whether DNMT1 can affect breast cancer metastasis in vivo, MDA-MB-231-shCtrl cells or MDA-MB-231-shDNMT1 cells were injected into the tail veins of BALB/c female nude mice." (PMID 36273188, 2022). "We next explored whether DNMT1 can affect breast cancer cell motility." (PMID 36273188, 2022).
breast cancer (continued). "Therefore, novel DNMT1 inhibitors such as azacitidine, decitabine, and guadecitabine, which can make cancer patients sensitive to immune checkpoint blockade therapy, have shown potential antitumor effects in breast cancer cells." (PMID 35743249, 2022). "In addition, DIM could effectively increase the sensitivity of MCF-7 and T47D breast cancer cells to PTX by downregulating KLF4 methylation through inhibiting DNMT1." (PMID 34150611, 2021). "Additionally, another oncogenic circRNA in breast cancer is circ-Dnmt1." (PMID 34335937, 2021). "Therefore, we hypothesized that SOX2 directly transactivates DNMT1 expression and thereby alters the methylation landscape and inhibits FOXO3a expression in breast cancer." (PMID 31296961, 2020). "Indeed, ZC3H18 depletion enhanced E2F1 binding to DNMT1 in ovarian cancer but not in breast cancer cells, suggesting that loss of ZC3H18 leads to E2F1-DNMT1 repressor complex formation in ovarian cancer cells." (PMID 31604914, 2019). "The altered expression of DNMTs, encoding DNMTs (DNMT1, DNMT3a, and DNMT3B) could result in global changes of methylation in leukemia cells and breast cancer stem-like cells, while DNMT1, DNMT3A, and DNMT3B are all upregulated in most cancer types (8, 6, and 9, respectively) in this study." (PMID 31828117, 2019). "Indeed, ectopic expression of DNMT1 activated breast stromal fibroblasts and enhanced their pro-carcinogenic effects both in vitro and in orthotopic mice model of breast cancer, while specific DNMT1 knockdown suppressed breast myofibroblasts and inhibited their tumor-promoting capacities." (PMID 29416775, 2018). "Furthermore, BRCA1-mutated breast cancer is associated with reduced DNMT1 transcription when compared with non-mutated breast cancer." (PMID 30558184, 2018). "Thus, DNMT1 inhibition may stimulate upregulation of MHC-I in a variety of breast cancers, and potentiate anti-tumor immunity." (PMID 29339738, 2018). "Besides, DNMT1 was conversely associated with miR-148a/152 expression, which highlighted a potential miR-148a/152-DNMT1 regulatory framework might exist in breast cancer." (PMID 28574848, 2017). "We speculate that ERα facilitates drug resistance mainly through randomly inactivating genes required for killing breast cancer cells in the case of its epigenetic regulation, since ERα-activated-DNMT1 was dominantly involved in drug-induced global DNA hypermethylation." (PMID 26980709, 2016). "Subsequent to determination of the ERα activating role in DNMTs genes, we evaluated the role of ERα-induced DNMTs up-regulation in acquired drug resistance of breast cancer cells by testing whether alteration of DNMT1 and DNMT3b expression change drug sensitivity of breast cancer cells." (PMID 26980709, 2016). "In addition, work in breast cancer cell lines demonstrated that HDAC1 maintains the chaperone, hsp90, in a deacetylated state, allowing its association with and preventing proteasomal degradation of DNA methyltransferase 1 (DNMT1)." (PMID 25474141, 2015). "Furthermore, DNMT1 was found in breast cancer and verified as a target for miR-148." (PMID 25580536, 2015). "Notably, although the methylation patterns and mRNA expression of DNMT1 showed no significant change in non-BRCA1-mutated breast cancer, the protein expression of DNMT1 is up-regulated." (PMID 24502362, 2014). "Interestingly, DNMT1 and DNMT3a were overexpressed in only 5 and 3% of breast carcinomas." (PMID 24822169, 2014). "Furthermore, an interaction between DNMT1 and miR-148a/152 was found in breast cancer." (PMID 23683438, 2013). "Thus, breast cancer appears as the second, after glioma, in which we observed that the DNA hypomethylation characterizing the tumor cells is correlated with the decrease of Dnmt1/PCNA interactions." (PMID 21470401, 2011).
breast cancer (continued). "DNMT1, along with DNMT3A and DNMT3B, is frequently upregulated in breast cancer tissues compared to normal breast tissue." (PMID 41602389, 2026). "At the molecular level, DNMT1 overexpression promotes hypermethylation of tumor suppressor gene promoters (including ERα and BRCA1), which leads to their silencing and enhances breast cancer aggressiveness, particularly in ER-negative and HER2-positive tumors." (PMID 41602389, 2026). "n breast cancer, piR‐651 and PIWIL2 recruit DNMT1 to induce PTEN promoter methylation, while piRNA‐823 upregulates DNMT1, DNMT3A, and DNMT3B, resulting in APC gene hypermethylation." (PMID 40761481, 2025). "This study seeks to address these knowledge gaps by exploring the regulatory role of DNMT1 in RASSF1A methylation and its impact on breast cancer brain metastasis." (PMID 41381440, 2025). "The DNA methyltransferase DNMT1 induces hypermethylation of the promoter of MEG3 and inhibits its expression, which then promotes the growth of breast cancer cells through the regulation of the miR-494-3p/OTUD4 axis." (PMID 41050073, 2025). "In contrast, our findings provide evidence of a direct functional interaction between DNMT1 and RASSF1A in the context of breast cancer brain metastasis, thereby expanding upon prior studies." (PMID 41381440, 2025). "Increased expression of DNMT1, DNMT3A, and DNMT3B was found in various cancers such as breast cancer, pancreatic cancer, lung cancer, hematological malignancies, and head and neck squamous cell carcinoma." (PMID 40507223, 2025). "Therefore, establishing an effective detection method for plasma DNMT1, which can convert single baseline static prediction into an early dynamic assessment during diagnosis and treatment, is of great importance for the prognosis and survival of breast cancer patients." (PMID 40317882, 2025). "To further evaluate the clinical significance of DNMT1 and RASSF1A in breast cancer patients, we performed survival analyses using transcriptomic data from the TCGA-BRCA cohort." (PMID 41381440, 2025). "DNA methylation is facilitated by DNA methyltransferases (DNMTs) such as DNMT1, DNMT3A, and DNMT3B, all of which are overexpressed in breast cancer patients with advanced clinical disease stages." (PMID 40427627, 2025). "For example, the oncogenic lncRNA TINCR brings DNMT1 to the promoter of miR-503-5p, resulting in hypermethylation and decreased expression, which in turn leads to increased STAT3 levels and promotes breast cancer progression." (PMID 40843360, 2025). "By integrating microfluidic sorting with single-cell sequencing, we aimed to delineate the role of DNMT1 in modulating RASSF1A methylation and to uncover potential molecular pathways involved in early breast cancer brain metastasis." (PMID 41381440, 2025). "This study investigates the role of DNA methyltransferase 1 (DNMT1) in regulating the methylation of RASSF1A and its contribution to breast cancer brain metastasis." (PMID 41381440, 2025). "The correlation matrix demonstrated a significant relationship between DNMT1 activity and both the pathological staging and TNM status of breast cancer patients." (PMID 40317882, 2025). "β-sitosterol inhibited DNMT1 and HDAC1 overexpression and cancer cell migration and suppressed some histone methylation marks induced by hydrogen peroxide in a human breast cancer cell line." (PMID 39941940, 2025). "TAMs support DNMT1 overexpression through the IL-6-pSTAT3-ZEB1-DNMT1 pathway, that in turn supports breast cancer invasion." (PMID 39660126, 2024). "CENP-A acts as a transcriptional regulator and promotes DNMT1 (DNA Methyltransferase 1)-mediated PLA2R1 (Phospholipase A2 Receptor) promoter methylation, thereby reducing the expression level of PLA2R1 and augmenting breast cancer progression." (PMID 39273649, 2024). "DNMT1 was reported to be overexpressed in the MCF-7 and T47D breast cancer cell lines, and its downregulation led to cell proliferation inhibition and the induction of apoptosis." (PMID 38257347, 2024).
breast cancer (continued). "The results showed that DNMT1 and HDAC1 expression was significantly upregulated in breast cancer tissues vs. normal tissues." (PMID 38490978, 2024). "Although, either silencing of DNMT1 or inhibition of HDAC1 & HDAC2 were able to reduce cell migration even after 24 h, both knockdown of DNMT1 and TSA treatment synergistically inhibited migration of MDA-MB-231 breast cancer cells significantly higher." (PMID 36774386, 2023). "In summary, we exhibited a feedback regulation loop formed by PAX5, miR-142, and DNMT1/ZEB1, which play crucial roles in breast cancer development." (PMID 37403081, 2023). "PiRNA-651 recruits DNMT1 to the promoter region of tumor suppressor gene PTEN via PIWIL2, thereby reducing its expression levels and promoting proliferation and invasion of breast cancer cells." (PMID 37325054, 2023). "Studies have shown that DNMT1, DNMT3A and DNMT3B are usually highly expressed in patients with advanced breast cancer." (PMID 37298314, 2023). "Reduced FOXO3a expression, orchestrated by DNA methyltransferase 1 (DNMT1), emerges as a driving force for proliferation and tumorigenesis due to increasing the population of breast cancer stem cells." (PMID 38068934, 2023). "In contrast, the treatment of breast cancer cells with SFN resulted in global DNA hypomethylation, DNA methyltransferase 1 (DNMT1) and DNMT3B deactivation, cell cycle arrest, and senescence." (PMID 37111207, 2023). "MiR-152 targets DNMT1 and downregulates the expression of DNMT1, which helps restore cadherin 1 (CDH1) gene expression and obstructs the migration of breast cancer cells." (PMID 37298314, 2023). "In breast cancer, a negative regulatory loop involving SETD7 and DNA methyltransferase 1 (DNMT1) has been observed." (PMID 38036730, 2023). "By joint analysis of gene expression data from previous studies, we constructed interrelationships of mainly CRHBP, ICAM1, PLAGL1, DNMT1, CNTLN, DKK1, and EGR2 with preterm birth, infant disease, and breast cancer." (PMID 36788602, 2023). "The expression of PAX5 was significantly down-regulated in breast cancer tissues, while the expression levels of DNMT1 and ZEB1 were both up-regulated in breast cancer tissues, compared with normal tissues." (PMID 37403081, 2023). "For instance, the upregulation of UHRF1 in breast cancer was shown to result in hypermethylation and inhibition of BRCA1 by forming an inhibitory transcriptional complex consisting of HDAC, DNMT1, and G9a over its promotor." (PMID 36077796, 2022). "For example, the upregulation of DNMTs, such as DNMT1, DNMT3A, and DNMT3B, is correlated with endocrine therapy resistance in ER+ breast cancer." (PMID 35453496, 2022). "In triple-negative breast cancer (TNBC), the most aggressive subtype of breast cancer, the long noncoding RNA LINC00152 has been shown to promote TNBC tumourigenesis by activating DNMT1." (PMID 35838271, 2022). "It has been reported that DNMT1 and DNMT2B were highly expressed in breast cancer, contributing to cancer progression and metastasis through DNA methylation." (PMID 35743249, 2022). "Taken together, DNMT1, PAS1, and PH20 comprise a regulatory axis to control breast cancer growth and metastasis." (PMID 35307730, 2022). "Herein, we measured DNMT1, MEG3, miR-494-3p and OTUD4 expression, verified the interaction between them, and then discussed the impact of them on biological function of breast cancer cells." (PMID 35109842, 2022). "Briefly, our results demonstrated that, DNMT1 induced methylation of MEG3 promoter, and played a key role in breast cancer growth throughmiR-494-3p/OTUD4 axis." (PMID 35109842, 2022). "LncRNA MALAT1 increased the expression of DNMT1, DNMT3A and DNMT3B and inhibited the BRCA1 and PTEN expression, leading to regulating of herceptin sensitivity in HER2-positive breast cancer." (PMID 35620052, 2022).
breast cancer (continued). "lncRNA PHACTR2-AS1 inhibited the proliferation, invasion, and migration of breast cancer cells by suppressing PH20 expression, which is mediated by DNMT1 methylation." (PMID 36276278, 2022). "The only partially relevant work is that of Sharma and Tollefsbol where a mixture of two dietary phytochemicals (Sulforaphane and Genistein) and butyrate inhibits DNMT1 expression in MDA-MB-231 and MCF-7 breast cancer cells." (PMID 36082029, 2022). "Increased DNMT transcript expression, including DNMT1, DNMT3a, and DNMT3b, in breast cancer tissues, suggests that DNMTs are involved in breast carcinogenesis." (PMID 35327559, 2022). "However, in breast cancer cell lines, this combination suppressed cell proliferation by increasing the mRNA and protein levels of Brca1 due to decreased promoter methylation, the downregulation of both DNMT1 expression and miR-29b, and the upregulation of TET1 and DNMT3." (PMID 35327559, 2022). "Recently, piR-823 increased the expression of DNMTs, including DNMT1, DNMT3A and DNMT3B, enhanced APC DNA methylation and subsequently activated Wnt pathway, leading to induction of CSCs in luminal breast cancer." (PMID 35620052, 2022). "DAC, as a DNMT1-specific inhibitor and FDA-approved drug, is a promising drug for breast cancer treatment." (PMID 36273188, 2022). "For example, lncRNA 01638 downregulation repressed the expression of DNMT1, DNMT3A and DNMT3B, and increased the expression of PTEN and BRCA1, resulting in inhibition of proliferation and invasion in HER2-positive breast cancer cells." (PMID 35620052, 2022). "Expression of NSUN1, NSUN2, NSUN5, DNMT1, DNMT3A, DNMT3B, and ALYREF was significantly increased, but DNMT2 and TET2 expression was markedly decreased in breast cancer tissues when compared with normal breast tissues." (PMID 35812757, 2022). "By cooperating with DNMT1, EZH2 knockdown led to DNA demethylation and consequently upregulated miR-124-3p, which suppressed its target CCL2 expression in breast cancer cells, leading to TAMs M2 polarization restraint." (PMID 36038549, 2022). "For example, in MDA-MB-231 breast cancer cell line, SIRT1 reduced the inhibitory effect exerted by DNMT1 on tumor suppressor genes ERα and CDH1." (PMID 35215560, 2022). "DNMT1 and miR-494-3p were highly expressed while MEG3 and OTUD4 were lowly expressed in breast cancer cells." (PMID 35109842, 2022). "DNMT1-regulated hypermethylation of the TSG RUNX3 promoter region is a new insight and an early event in breast cancer predominantly in TNBC (triple-negative breast cancer)." (PMID 35898303, 2022). "First, we utilized western blot and qRT-PCR to assess DNMT1 and MEG3 levels in breast cancer cell lines (MDA-MB-231, SUM 149) and normal breast epithelial cell line (MCF10A)." (PMID 35109842, 2022). "One study identified 16 SNPs in DNMTs, including 5 SNPs in DNMT1, 6 SNPs in DNMT3A, 3 SNPs in DNMT3B, 1 SNP in DNMT3L and 1 SNP in DNMT2 in 408 breast cancer patients and 469 controls." (PMID 35620052, 2022). "The lentivirus carrying KLF4 and DNMT1 gene or shRNA targeting DNMT1 were used to overexpress KLF4 or knockdown DNMT1 in MCF-7 and T47D breast cancer cells and the role of KLF4 and DNMT1 in regulation of PTX sensitivity was investigated." (PMID 34150611, 2021). "To further investigate the mechanism of action of DIM in enhancing PTX sensitivity, we determined the expression levels of DNMT1 and KLF4 in breast cancer MCF-7 and T47D cells after treatment with DIM." (PMID 34150611, 2021). "SFN reduced the expression of DNMT1 and DNMT3B in three breast cancer cell lines (MCF-7, MDA-MB- 231, and SK-BR-3) with a significant increase in the expression of p21 and p27, and down-regulation of miR-23b, miR-92b, miR-381, and miR-382." (PMID 34835969, 2021).